EGFR (epidermal growth factor receptor)
Diseases named in the same sentence as EGFR in open-access papers (continued):
Sharing a sentence is not in itself a finding about the gene and the disease.
xerostomia (3 papers, 2021 to 2023). Dryness of the mouth resulting from reduced salivary secretion. "Collectively, nitrate effectively prevented IR-induced xerostomia via the EGFR–AKT–MAPK signaling pathway." (PMID 34581269, 2021). "The PPI network genes IL6R, EGFR, NFKB1, MPO, and TNFSF13B constitute a possible biomarker signature of xerostomia." (PMID 35268532, 2022). "The IL6R, EGFR, NFKB1, MPO, and TNFSF13B genes might all have implications in the diagnosis and intervention of xerostomia." (PMID 35268532, 2022). "Furthermore, no clinical trials were identified that have evaluated EGFR as a drug target in xerostomia, dry mouth, or Sjögren’s Syndrome." (PMID 35268532, 2022).
ZIKV infection (3 papers, 2018 to 2022). "For example, two hours after ZIKV infection, both in vivo and in vitro, the induced LDs were transiently upregulated and controlled by the epidermal growth factor receptor (EGFR)." (PMID 36293437, 2022). "A more recent model indicated that ZIKV infection induces the activation of EGFR and further transduction of the MAPK/ERK signaling cascade." (PMID 35847084, 2022). "Furthermore, similar to JEV infection, the depression of ZIKV infection was also found in EGFR-KO hBMECs." (PMID 35847084, 2022). "Many of these proteins have been shown to be related to cellular functions of neural cells, and are found to play roles in cell signaling processes, such as DCX, EGFR, and GAP43, indicating the alteration of multiple cell signaling pathways in NPC by ZIKV infection." (PMID 29922247, 2018).
acanthosis nigricans (2 papers, 2010 to 2022). A melanotic cutaneous lesion that develops in the axilla and other body folds. "In addition to the cases mentioned in this paper, other rare disorders that have matched with therapeutic options include non-ketotic hyperglycinemia, MAPK8IP3-related disorder, EGFR-associated acanthosis nigricans, and SETD1A-related disorder." (PMID 36248623, 2022).
acinar lung adenocarcinoma (2 papers, 2024 to 2025). A morphologic variant of lung adenocarcinoma characterized by the presence of acinar structures composed of columnar or cuboidal cells. "The other research indicated that EGFR mutations occurred most frequently in acinar lung adenocarcinoma and least frequently in solid lung adenocarcinoma." (PMID 40182027, 2025). "The present report delineates a rare case of acinar lung adenocarcinoma harboring an L858R point mutation in exon 21 and a compound S768I EGFR substitution mutation." (PMID 38494473, 2024).
acute pancreatitis (2 papers, 2024 to 2025). An acute inflammatory process that leads to necrosis of the pancreatic parenchyma. "Previous experiments have showed that overexpressing EGFR and ErbB4 protects mice from acute pancreatitis." (PMID 40702576, 2025).
adenosarcoma (2 papers, 2017 to 2025). A low grade malignant neoplasm characterized by the presence of a benign epithelial component (tubular and cleft-like glands) and a low grade sarcomatous component that contains varying amounts of fibrous and smooth muscle tissues.
adnexal carcinomas (2 papers, 2012 to 2015). "The lack of correlation between the protein expression and polysomy/gene amplification suggests that molecular mechanisms other than gene amplification may play a role in EGFR overexpression in adnexal carcinomas." (PMID 23056620, 2012). "In skin adnexal carcinomas, it was suggested that molecular mechanisms excluding gene amplification may have a role in EGFR overexpression because of lack of correlation between the polysomy/ gene amplification, and protein expression." (PMID 25815059, 2015).
adrenal tumors (2 papers, 2012 to 2013). "To investigate whether the EGFR inhibitor gefitinib could increase the antitumor effect of DXR against the adrenal tumors of transgenic mice, we evaluated the antitumor activity of gefitinib alone and in combination with unencapsulated or liposomal DXR." (PMID 23930205, 2013). "However, we could not rule out the possibility that gefitinib potentiates the cytotoxic action of DXR by inhibiting EGFR signaling in adrenal tumor cells." (PMID 23930205, 2013).
AIDS (2 papers, 2013 to 2014). A syndrome resulting from the acquired deficiency of cellular immunity caused by the human immunodeficiency virus (HIV). "This study points to an association of high risk HPV with over expressions of p16INK4A and EGFR proteins in AIDS-associated SCCC." (PMID 24572046, 2014). "The present study therefore compared PCR-based detection of HPV with immunohistochemical expressions of p16INK4A, EGFR and pEGFR; and the potential value of use of these biomarkers as indicators of HPV positivity in selected cases of HIV/AIDS-related SCCC." (PMID 24572046, 2014).
anal tumor (2 papers, 2010 to 2017). "The others pretreatment variables with significant predictive value are anal tumor distance, cyclin D1, p21, EGFR and VEGF in biopsies and neutrophil lymphocyte ratio in blood samples." (PMID 28938543, 2017). "However, the high levels of EGFR expression seen in anal tumours suggest that trials to investigate the activity of both TK inhibition and antibody inhibition of EGFR signalling are merited." (PMID 21063399, 2010).
anaplastic ependymoma (2 papers, 2019 to 2021). Anaplastic ependymoma is a rare, malignant type of ependymoma that most often arises in the supratentorial region of the brain of children and young adults and that manifests with variable symptoms including headaches, nausea, vision impairment, memory loss and difficulty walking. "The tumor in our case is grade III anaplastic ependymoma and it stained negatively for EGFR, confirming this observation." (PMID 32612806, 2019).
anaplastic large cell lymphoma (2 papers, 2014 to 2019). Anaplastic large cell lymphoma (ALCL) is a rare and aggressive peripheral T-cell non-Hodgkin lymphoma, belonging to the group of CD30-positive lymphoproliferative disorders, which affects lymph nodes and extranodal sites. "In recent years, a few biomarkers have emerged as prognostic or predictive factors in non-small cell cancer which include epidermal growth factor receptor (EGFR), ALK (Anaplastic Large Cell Lymphoma) fusion Gene, K-ras oncogene and others." (PMID 25162713, 2014).
apocrine carcinomas (2 papers, 2010 to 2015). "The other markers showed that typical invasive apocrine carcinomas are AR-positive, ER-negative and EGFR positive." (PMID 20712882, 2010). "The role of EGFR inhibitors remains unclear in eccrine-apocrine carcinomas with protein overexpression." (PMID 25815059, 2015).
asbestosis (2 papers, 2013 to 2016). A lung disorder caused by inhalation of asbestos fibers. "They observed significantly higher sEGFR values in the first group of cases compared to the other ones, concluding that the soluble isoform of the EGFR may be elevated in the early stages of carcinogenesis in asbestosis patients." (PMID 27104520, 2016). "A soluble fragment of the EGFR extracellular ligand domain can be detected by ELISA in the blood of cancer patients, including NSCLC patients, and may also be elevated at an early stage of carcinogenesis in asbestosis patients." (PMID 23384026, 2013).
ascending colon cancer (2 papers, 2019 to 2025). A malignant neoplasm involving the ascending colon. "Patient A, a 67‐year‐old male, was diagnosed with metastatic ascending colon cancer and exhibited EGFR membrane localization." (PMID 39560161, 2025). "We report a case of metastatic ascending colon cancer complicated by PDs that was successfully treated with the anti-EGFR antibody Pmab plus CAT." (PMID 31103951, 2019).
Ascites (2 papers, 1997 to 2022). Accumulation of fluid in the peritoneal cavity (between the layers of the peritoneum that lines the abdomen). "In multivariate analysis only the presence of ascites, p21 levels and epidermal growth factor receptor status retained an independent prognostic role." (PMID 9166952, 1997). "Given the finding of the same EGFR rare mutation in peritoneal effusion without other EGFR-TKI resistance mutations, the patient received afatinib with a tremendous response." (PMID 35712479, 2022).
bacterial pneumonia (2 papers, 2018 to 2025). Acute infection of the lung parenchyma caused by bacteria (e.g., Streptococcus pneumoniae, Haemophilus influenzae, Chlamydia pneumoniae, Mycoplasma pneumoniae, and Legionella pneumophila). "In a murine model of bacterial pneumonia, luteolin demonstrated the capacity to inhibit M1 macrophage polarization by suppressing the EGFR/PI3K/AKT/NF-κB and EGFR/ERK/AP-1 signaling pathways." (PMID 41246326, 2025).
benign epithelial neoplasm (2 papers, 2021 to 2022). A neoplasm arising from the epithelial cells. "Here we review the landscape of EGFR mutations in SNSCC, with a particular focus on SNSCC associated with inverted sinonasal papilloma (ISP), a benign epithelial neoplasm." (PMID 35053553, 2022).
biliary atresia (2 papers, 2020 to 2025). A rare, biliary tract disease characterized by progressive obliterative cholangiopathy of the intra- and extrahepatic bile ducts, occurring in the embryonic/ perinatal period, leading to severe and persistent neonatal jaundice and acholic stool. "The fixed points, PF2 and PF3, and the limit cycle CL1 show an increase in EGFR and TGFß with a total ABRS equal to 84.6% and can represent the physiologic behavior of the familial biliary atresia." (PMID 41465403, 2025). "A recent study showed that ARF6 is involved in the EGFR pathway and is critical for proper bile duct formation, which suggests a non-superfluous role for USP6 in biliary atresia." (PMID 32848883, 2020).
bladder squamous cell carcinoma (2 papers, 2019 to 2025). A squamous cell carcinoma of the bladder arising from metaplastic epithelium. "The conjugate showed the best efficacy against bladder squamous cells carcinoma cells with the highest EGFR expression and significantly reduced tumor growth in a BC mouse xenograft model." (PMID 41471825, 2025). "On the other hand, bladder squamous cell carcinoma cell lines such as UMUC-5 and ScaBER were highly enriched in cell surface EGFR, but showed very low levels of cell surface HER2." (PMID 30765854, 2019).
Blindness (2 papers, 2022 to 2023). Blindness is the condition of lacking visual perception defined as a profound reduction in visual perception. "Some evidence also indicates that the engagement of the EGFR can induce proliferation, differentiation, and migration of RPE cells, contributing to proliferative vitreoretinopathy and blindness." (PMID 37936170, 2023). "Similarly, EGFR induces proliferation, differentiation and migration of RPE cells, contributing to proliferative vitreoretinopathy and blindness." (PMID 37936170, 2023).
brain astrocytoma (2 papers, 2020 to 2022). A astrocytoma (excluding glioblastoma) that involves the brain.
Brain atrophy (2 papers, 2023 to 2024). Partial or complete wasting (loss) of brain tissue that was once present. "However, during neurological decline and brain atrophy, EGFR reappears in brain cells to maintain a balanced neuron bank." (PMID 39354858, 2024).
brainstem glioma (2 papers, 2011 to 2025). "Among patients with brainstem gliomas, those with EGFR overexpression had a median progression-free survival (10.1 months) longer than EGFR-negative cases (6.3 months)." (PMID 41050069, 2025). "In brainstem gliomas, patients with EGFR overexpression demonstrated a median progression-free survival of 10.1 months, which was significantly longer than that observed in EGFR-negative cases (6.3 months)." (PMID 41050069, 2025).
bronchopulmonary dysplasia (2 papers, 2018 to 2024). Bronchopulmonary dysplasia is a chronic respiratory disease that results from complications related to lung injury during the treatment of infant acute respiratory distress syndrome in low-birth-weight premature infants or from abnormal lung development in older infants. "In another study, fetal rat lung fibroblasts were used to investigate the role of the epidermal growth factor receptor (EGFR) in stretch-dependent mechanical lung injury as a result of ventilator-induced lung injury (VILI) linked to bronchopulmonary dysplasia (BPD)." (PMID 39068387, 2024). "Abnormal EGFR signaling may contribute to the development of bronchopulmonary dysplasia." (PMID 30005089, 2018).
cancer of the parotid gland (2 papers, 2011 to 2024). "Moreover, when treating cancer of the parotid gland, which the facial nerve passes through, NIR-PIT using the EGFR Affibody–IR700Dye conjugate can remove cancer cells as far into the gland as possible while preserving normal nerve cells." (PMID 38542206, 2024).
Castleman disease (2 papers, 2014 to 2022). Castleman disease (CD) is a benign lymphoproliferative disorder that may present as a localized or multicentric form. "Follicular dendritic cells in both Castleman disease and FDCS express high levels of epidermal growth factor receptor, which along with its ligands, drives FDC proliferation and survival." (PMID 35941667, 2022). "FDCS and non-neoplastic FDCs of Castleman’s disease both express epidermal growth factor receptor (EGFR) which may promote FDC persistence leading to FDCS." (PMID 25405526, 2014).
cerebral hemisphere tumors (2 papers, 1991 to 2021). "Older patients with IDH-wildtype cerebral hemisphere tumors tend to express greater levels of EGFR protein." (PMID 33707521, 2021). "Age, combined with IDH-wildtype cerebral tumor, was predictive of greater EGFR protein expression in human tumors." (PMID 33707521, 2021).
cervical (2 papers, 2016). "To further validate our hypothesis that GW627368X hinders cervical carcinogenesis via EP4/EGFR interactive signaling, we studied the phosphorylation status of key effector molecules after exogenously over-expressing PGE2." (PMID 27010855, 2016).
Chlamydia infection (2 papers, 2017 to 2021). "In contrast, Chlamydia infection was recovered by the overexpression of EGFR in CHO-K1 cell lines." (PMID 35173712, 2021).
Cholestatic liver disease (2 papers, 2017 to 2026). "Animal experiments demonstrated that melatonin alleviated inflammation and fibrosis in cholestatic liver disease, downregulated MMP9 expression, and upregulated the expression of EGFR, AKT, and phosphorylated AKT." (PMID 41758906, 2026). "The functional consequence of EGFR signaling in cholestatic liver disease was investigated in Mdr2−/− mice lacking EGFR expression in hepatocytes and cholangiocytes." (PMID 27568040, 2017).
chronic rhinosinusitis (2 papers, 2023 to 2024). Chronic form of sinusitis. "Heterozygous EGFR exon 20 amino acid insertions (ex20ins), located between amino acids 768–774, were observed in 45% of IP, 28.5% of IP-SCC, and 0% of SNSCC and chronic sinusitis cases." (PMID 37109043, 2023). "A deduced amino acid substitution in EGFR was observed in five IP cases (25%), four IP-SCC cases (57.1%), one SNSCC case (4.5%), and zero chronic sinusitis cases (0%)." (PMID 37109043, 2023). "Heterozygous EGFR ex20ins were observed in nine IP cases (45%), two IP-SCC cases (28%), and zero SNSCC and chronic sinusitis cases." (PMID 37109043, 2023). "EGFR ex20ins was frequently detected in IP and IP-SCC but not in SNSCC and chronic sinusitis." (PMID 37109043, 2023).
cleft palate (2 papers, 2021 to 2022). Cleft palate is a fissure type embryopathy that affects the soft and hard palate to varying degrees. "However, some previous studies have described that EGFR might be involved in cleft palate development in mice due to the fact, that EGFR-deficient mice have very high incidence of cleft palate." (PMID 34393631, 2021). "Although the penetration of the cleft palate phenotype is not high, EGFR knockout mice show cleft palate due to defects in MEE seam disruption." (PMID 34897389, 2022).
co-infection (2 papers, 2025 to 2026). "In H1650 cells, all c-MET/EGFR-dual-targeting approaches, i.e., co-infection, co-expression, or expression of the trispecific Db-TriTE, were superior to mono-targeting of EGFR and c-MET." (PMID 41552759, 2026). "Taking into consideration the TCE production and oncolytic activity data, we decided to focus our analysis on dual-targeting with the Db-TriTE-encoding virus (Ad5/3-DMFE), co-expression of scDb-cMET and taFv-EGFR (Ad5/3-DMTtE), and co-infection (Ad5/3-tE + Ad5/3-DM)." (PMID 41552759, 2026). "Therefore, SRC and EGFR may serve as key targets for probenecid in treating SARS-CoV-2/RSV co-infection, while HSP90AA1 may play a lesser role." (PMID 40371107, 2025). "Subsequently, we obtained the top 16 hub targets of probenecid for SARS-CoV-2/RSV co-infection, namely, AKT1, ALB, EGFR, CASP3, CTNNB1, SRC, HSP90AA1, and so on." (PMID 40371107, 2025).
Conjunctiva Cancer (2 papers, 2010 to 2020). "Immunohistochemistry and qPCR data suggest that activation and expression of the EGFR signaling pathway is related to disease progression of conjunctival cancer." (PMID 20498858, 2010).